CD4 (CD4 molecule)
Diseases named in the same sentence as CD4 in open-access papers (continued):
Sharing a sentence is not in itself a finding about the gene and the disease.
infection (continued). "As previously documented, the major target of this depletion appears to be the central memory CD4+ T cell subset that was reduced from a mean of >600 to <200 cells/μl of blood within 2 weeks post infection." (PMID 24603870, 2014). "There was a striking difference in proliferation of CD4+ and CD8+ T cells from dLNs of low and high dose-infected mice with high dose infection inducing significantly (p<0.05–0.01) more CD4+ T cell proliferation compared to low dose infections." (PMID 25412267, 2014). "The faster the CD4+ T cells decline, the higher the rate of progression toward disease and death—that is, the higher the virulence of the infection in the sense of evolutionary ecology." (PMID 25226169, 2014). "Th1, Tfh, Th17, and Th2 cells are considered conventional CD4+ T cells, whereas regulatory CD4+ T cells (Tregs) maintain peripheral tolerance and down-regulate responses in the context of numerous infections." (PMID 25051576, 2014). "Follicular dendritic cells (FDCs) have been recognized as a major reservoir for virus in lymphoid tissues, facilitating infection of CD4 T cells." (PMID 25610441, 2014). "CD4+ T cell numbers derived from flow cytometry and viable cell counts were reported relative to mock infection." (PMID 24495380, 2014). "We observed a significant increase in interleukin-17 (IL-17) positive CD4 + T cells at convalescent versus acute stage of infection using an intracellular cytokine staining assay." (PMID 24615129, 2014). "HIV-1 is decorated with trimeric glycoprotein spikes that enable infection by engaging CD4 and a chemokine coreceptor, either CCR5 or CXCR4." (PMID 24884925, 2014). "Together, these results demonstrate that primary CD4+ T cells have an increased rate of glycolysis upon infection with HIV-1." (PMID 25421745, 2014). "The proliferative capacity of HIV-specific CD4 T cells is selectively impaired in vertically infected children with uncontrolled viral replication, but, in contrast to adult infection, can be rescued with administration of ART." (PMID 25161656, 2014). "The expression of the Tfh classical markers CxCR5 and PD-1 in lymph node CD4 T cells increased progressively after infection at the transcript and protein levels, though without statistical value." (PMID 24763747, 2014). "This discrepancy is likely due to the preservation of mucosal CD4+ T cells in early infection, as our previous study had shown that the depletion of Th17 cells, in chronic SIV infection, results in the increased dissemination of pathogenic S. Typhimurium." (PMID 25166758, 2014). "Ad5hr infection induced polyfunctional CD4 and CD8+ T cells specific for the Ad5 hexon protein in all of the animals." (PMID 25203111, 2014). "In, the mass action term k1xv used to model infection of CD4+ T cells by free virions is biologically problematic for several reasons." (PMID 24829609, 2014). "Altogether, these data suggest a role of CD4+ T-cells in protective immunity to pre-erythrocytic-stage infection, the mechanisms of which are not yet completely understood." (PMID 25628621, 2014). "Demonstration of CD4 cytolytic activity in these infections suggests CD4 cells have a more direct role in viral clearance than was previously appreciated." (PMID 24586481, 2014). "The IFN-γ response by CD4+ T cells occurred in both draining LNs and the epithelial and dermal layers of infected skin, including regions a considerable distance away from infection foci in the epithelium." (PMID 25121482, 2014). "In our study, we found that immunization with pcDNA-mGMCSF-Pxn1 induced the highest frequency of IFN-γ+TNF-α+IL-2+ CD4+ T cells and showed the highest level of protection of mice from L. major challenge infection." (PMID 25500571, 2014). "It will be interesting to perform transfer experiments to test the protective effect of serum from infection/cure MHC II animals enriched with CD4+ T cells from infection/cure wildtype animals." (PMID 24620841, 2014).
infection (continued). "Depletion of CD4+ cells in mice that healed their low and high dose infections led to impaired parasite control following secondary challenge." (PMID 25412267, 2014). "Disseminated infection is quickly accompanied by CD4+ T cell depletion in the gastrointestinal (GI) tract." (PMID 25196380, 2014). "But interestingly the percentage of CD4+CD25+CD127low/− iTreg cells increases at late time point in SbR-LD infection and these cells also contributes to IL-10 production considerably." (PMID 25032977, 2014). "We report here that infection with HIV-1 further increases the glycolytic activity of activated primary CD4+ T cells and that preventing glycolysis in infected cells is associated with increased cell survival." (PMID 25421745, 2014). "For the protease inhibitors class, the factors associated with TDRM were log HIV-RNA load, age per 10 years, square root CD4 cell count, and recent infection." (PMID 25047543, 2014). "Sorted populations of CD44+CD62L−Ly6C+, CD44+CD62L−Ly6C−, or CD44+CD62L+ TCM T cells from chronic animals were labeled with a proliferation dye and co-transferred with dye-labeled naïve CD62L+GFP+CD4+ cells from naïve mice into infection-matched recipients." (PMID 25473946, 2014). "These can be revealed by redesigning ESAT-6 analogs in which the dominant epitope is removed, resulting in the engagement of protective CD4+ T cell responses that resist infection-driven terminal differentiation." (PMID 25157249, 2014). "In contrast, HIV-1 does not express this protein and is thus unable to generate productive infection in resting CD4+ T cells." (PMID 24811311, 2014). "Subsequently, the helper role of HCMV-specific CD4+ T-cells was reevaluated utilizing the murine CMV model of infection as well as in man, both in the immunocompetent and immunocompromised host." (PMID 25166270, 2014). "Despite fairly similar CD4 count recovery, HBC-infection was associated with a 3-fold increase in long-term mortality." (PMID 24533106, 2014). "Using the JRFL envelope, which has broad ability to infect different types of target cells in tissue culture experiments, we detect a preference for the infection of CD4 T cells in the different anatomical sites." (PMID 25299616, 2014). "Primary CD3/CD28 activated CD4+ T cells were infected with HTLV-1 in a dose dependent manner using an in vitro trans-infection system in which CD4+ T cells were co-cultured with HTLV-1 shedding MT-2 cells." (PMID 25521510, 2014). "Nine days after infection, there were fewer transferred CD4+ T cells in recipients that were developmentally exposed to TCDD compared with recipient offspring of vehicle-treated dams." (PMID 25051576, 2014). "Staining of skin sections with anti-IFN-γ antibodies confirmed the presence of IFN-γ-producing cells during the acute phase of infection, with both endogenous CD4+ and CD8+, as well as transgenic gBT-I and gDT-II TEFF cells contributing to this response." (PMID 25121482, 2014). "The ability to define a population of memory TFH cells in PBMC (pTFH) would help inform our understanding of CD4 T cell dynamics within lymphoid tissue during vaccination or infection." (PMID 24497824, 2014). "We observed a significant increase in the frequency of these cells among CD4+ T cells from 40 hours post infection (h p.i.) with a similar increase in the absolute number of Tregs." (PMID 25108672, 2014). "The CD4 T cell response was followed after infection of young and aged C57BL/6 mice with influenza virus using a tetramer specific for an immunodominant MHC class II epitope of the influenza virus nucleoprotein." (PMID 24999367, 2014). "Field studies of natural human Plasmodium infections and mouse models should complement each other to get a deeper understanding of the complex CD4+ T-cell response activated by these infections." (PMID 25628621, 2014). "A single (or a few) founder genetic lineage(s) establish the infection in the CD4+ cells localized in the mucosa at the port of entry." (PMID 24996694, 2014).
infection (continued). "Not only were NFL concentrations abnormally high in all of the HAD patients, they revealed a substantial prevalence of less evident or subclinical injury in the NA groups with low blood CD4 T-cell counts as well as during the early phase of infection." (PMID 25541953, 2014). "Upon Treg depletion prior to infection there was an increased infiltration of T cells as we observed an increased frequency of CD4+ and CD8+ T cells in the brain." (PMID 25391297, 2014). "Sts dKO mice had reduced levels of CD4+ effector T cells at 16 dpi, but had equivalent amounts at 28 dpi, and more at 6 weeks post infection." (PMID 24587276, 2014). "The effect of route of infection on CD4+ helper T cell function during RVFV infection remains to be evaluated in further detail." (PMID 24922480, 2014). "For HIV infection, siRNAs can inhibit viral replication in vitro by either directly targeting sequences of viral gene products or silencing essential host factors (EHFs), such as the HIV receptor CD4 or the CCR5 coreceptor required for productive infection." (PMID 24526828, 2014). "During natural infection or after subunit vaccination in mice, vigorous Th1 type CD4+ T cell responses are directed to the N-terminal immunodominant epitope ESAT-61–15, whereas other epitopes are masked." (PMID 25157249, 2014). "We used linear regression models to assess the association between ARSSS and log baseline viral load (VL), baseline CD4+ cell count, and log viral setpoint (sVL) (i.e. VL measured ≥90 days after infection or treatment interruption)." (PMID 25490090, 2014). "Memory CD4+ T-cells are the primary target of infection and account for the majority of virus seen in the blood of patients." (PMID 24651404, 2014). "The ability of DRAG mice to clear the infection was associated with development of antibodies (human IgM and IgG) and TNF-mediated CD4 and CD8 T cell responses to the blood stage parasites." (PMID 25266106, 2014). "In order to obtain greater insights into the genetic networks, main regulators and mechanisms associated with cell survival in a chronic infection, we have compared the cellular responses to acute and chronic types of SIV-infection of a human CD4+ T cell line." (PMID 25163480, 2014). "The frequencies and absolute numbers of peripheral CD4+ T cell numbers were also significantly reduced by day 14 post-infection." (PMID 25503264, 2014). "Purified and activated CD4+ T cells from two donors were infected with HIV-1 (WT) or HIV-1ΔVpu at a multiplicity of infection (moi) of 3 to ensure >90% infection." (PMID 25211072, 2014). "On day 8 post-infection, cells were collected and stained for extracellular expression of CD4 and CD25, and intracellular expression of IFN-γ, IL-4, IL-17A, and Foxp3." (PMID 24918929, 2014). "CKR-L3 is a five amino acid deletion mutant from NTR compared to CCR6 providing accelerated and better infection efficiency in the NP-2/CD4 cell system." (PMID 24980635, 2014). "Several studies have demonstrated that the infection starts with a small number of CD4+ T-cells infected with HIV that multiply before systemic viremia is established." (PMID 25313360, 2014). "Together, these data suggest that CD28 is essential for the expansion of central and effector memory CD4+ T cells during re-infection with N. brasiliensis." (PMID 24516382, 2014). "Examination by flow cytometry of the numbers of CD14+ monocytes and WC1+, CD4+ and CD8+ T cells in peripheral blood following infection showed only a transient reduction in the proportion of CD4+ cells at 4 dpi." (PMID 24559207, 2014). "The dissemination of HIV from an initial site of infection is facilitated by motile HIV-infected CD4+ T-cells." (PMID 24551068, 2014). "Similar to CD21− B cells, total numbers of CD4+CD8α+ T helper cells dropped less severely than CD4+CD8α− T helper cells in INOC gilts on 2 dpi after PRRSv infection." (PMID 25497114, 2014).
infection (continued). "In contrast, no significant alterations were detected in the differentiation phenotype of CD4 T cells in the blood or LNs during both acute and chronic stages of infection." (PMID 24763747, 2014). "To this end, we defined a tolerance phenotype for each individual by calculating the residual in a quadratic regression between an individual's CD4+ T-cell decline and viral load, controlling for the age at infection." (PMID 25226169, 2014). "Direct infection and destruction of CD4+ T cells, particularly the central memory subpopulation, contributes to the depletion of CD4+ T cells, especially in early HIV infection." (PMID 25505958, 2014). "The frequency of CCR5+ CD4+ T memory cells in blood increased at week 1 after primary Ad5hr infection (p<0.01), then returned to pre-infection levels." (PMID 25203111, 2014). "MIG and IL-12 are involved in T cell recruitment and differentiation respectively and have been shown in some human cohorts to be elevated during infection, and CD4+ T cells have been shown to contribute to hind limb swelling in mice." (PMID 24587470, 2014). "DCs can become infected at the site of entry of the virus (cis-infection) and they participate to the early transmission of HIV to the CD4 T cells (trans-infection)." (PMID 24489947, 2014). "Consistent with the results obtained in CIITA−/− mice, we found that CD4+ T cell-depleted mice, at day 18 after infection, still manifested significantly higher viral titers in the liver, whereas control IgG-treated animals had cleared the virus." (PMID 24466045, 2014). "In HIV-1, CD4+ T cells are a key target of infection, where depletion of these cells results in deterioration of the immune system and progression to AIDS." (PMID 24517971, 2014). "This is especially true in cases of CD4-mediated concomitant immunity, where protection against reinfection coincides with the persistence of a primary infection." (PMID 25473946, 2014). "Very little is known about the CD4+ T-cell response to Plasmodium pre-erythrocytic stages, or its regulation in natural infection either in humans or in experimental models." (PMID 25628621, 2014). "There has been relatively little functional and immunogenetic dissection of CD4 T-cell immunity to Salmonella in the context of human infection." (PMID 24891088, 2014). "Identification of class II MHC epitopes has been an active area of research for characterization of antigen-specific HCV and HIV CD4+ T cell responses in infection and vaccination and for construction of epitope-driven vaccines." (PMID 25339942, 2014). "Astrocytes lack the CD4 receptor, which is required for classical HIV-1 entry, and infection is thought to be both CD4 and coreceptor independent." (PMID 24587404, 2014). "We observed fewer CD4+ T cells at 28 dpi in the infected Sts dKO mice, but the levels increased to that of WT mice by 6 weeks post infection." (PMID 24587276, 2014). "Statistically significant increases in total percentages of CD4+IFNγ+, CD4+IL-2+, and CD4+TNFα+ T cells were detected post-infection relative to D0 (P<0.05, 0.01, and 0.05, respectively) following primary infection." (PMID 25397604, 2014). "We did detect CD4+ T cells within the epithelium at sites of infection, in addition to being present in the dermis, and keratinocytes can express class II molecules under certain inflammatory conditions, e.g. in response to (IFN)-γ." (PMID 25121947, 2014). "Previous studies have demonstrated that chronic pathogen infection induces an upregulation of the expression of CD4+CD25+ Tregs within the host and inhibits the response of antigen-specific CD4+ T cells." (PMID 24944616, 2014). "A similar time course of infection was performed on HeLa-CD4 cells that had been pre-treated with AZT." (PMID 24410916, 2014). "Ligation of OX40 had the same effect as in the Lm-2W infection, with the dramatic expansion of the 2W1S-specific CD4+ T cells (p = 0.003; median for control: 17 721, anti-OX40: 210 626)." (PMID 24771127, 2014).
infection (continued). "Our data demonstrate a consistent pattern of pro-inflammatory cytokine production by C. jejuni-specific CD4+ T cells following primary infection, which included IFNγ, TNF-α, IL-2, and the chemokine, MIP-1β." (PMID 25397604, 2014). "Nevertheless, in target cells expressing low levels of CD4 (white bars), infection was reduced by approximately ten fold in clinical isolates as compared to YU-2, largely recapitulating findings in macrophages." (PMID 24656066, 2014). "Data from the N. brasiliensis system furthermore suggest that numerically ILC2 cells comprise the major source of IL-13 following infection, out-numbering CD4+ T cells." (PMID 24942690, 2014). "Only peripheral monocytes and macrophages and CD4+ T lymphocytes migrating across the blood-brain barrier are infected and that infection is limited to the meninges and perivascular spaces." (PMID 25523827, 2014). "VCG activation of BMDC enhanced the secretion of proinflammatory cytokines, particularly IL-12 and TNF-α and chlamydial antigen presentation to infection-sensitized CD4+ T cells leading to enhanced proliferation and secretion of Th1-type cytokines." (PMID 25551828, 2014). "Human T cell lymphotropic virus type 1 (HTLV-1) is a CD4+ T cell-tropic virus that establishes a persistent infection in humans." (PMID 24699260, 2014). "It is generally believed that a vaccine will have at its core instigation of an antigen specific CD4+ T cell response which plays an important role in development of protective immunity against infection." (PMID 25061608, 2014). "Maximal impact in our modelling was observed if the uninfected G+ CD4+T cells, in addition to having reduced likelihood of productive infection, exhibited lower levels of bystander apoptosis over G- CD4+T cells." (PMID 24945407, 2014). "To identify the site of initial priming and expansion of M133 Tregs compared to Tconv, we first analyzed priming of M133 Tconv (Treg-depleted CD4 T cells) by transferring CFSE-labeled cells one day prior to infection." (PMID 25102154, 2014). "In general, protection against erythrocytic-stage infection is thought to be mediated by CD4+ T cells, which orchestrate the activation of effector cells and maintain the production of protective antibodies." (PMID 25373617, 2014). "We therefore aimed to assess the turnover of SIV DNA in resting CD4 T cells at different times post-infection." (PMID 24710023, 2014). "We have previously used this vector to determine that the majority of HIV-1 proviruses are directly silenced shortly after infection in both cell lines and primary CD4+ T cells." (PMID 24502247, 2014). "CD4+ T-cell depletion following infection and persistent immune activation can partially explain this low CD4+ T-cell recovery." (PMID 25293882, 2014). "Pathogen-specific antibodies secreted by B cells with CD4+ T helper cells enhancement are essential for clearance of parasitemia in the later stages of the infection." (PMID 25452745, 2014). "Flow cytometric analyses show that akin to observations during early infection, the percentage of proliferating CD4+ T cells was significantly (p<0.01) higher in high dose-infected mice compared to the low dose infected group." (PMID 25412267, 2014). "Chronic untreated HIV infection is characterized by general immune activation, immune dysregulation, high T cell turnover and a gradual decline of CD4+ T cells through infection and bystander activation induced apoptotic death." (PMID 25369333, 2014). "After S. Virchow infection, numbers of CD4+, CD8α+, and CD8β+ cells had increased in the ileum by five DPI, indicating a T helper and a cytotoxic T cell response had occurred." (PMID 26664914, 2014). "Results of ICS indicate a significant increase in IFNγ- and IL-17A-producing Prn-, FHA-, and Ptx-specific CD4+CD44+ T-cells after infection." (PMID 25137043, 2014). "We further show that our assay can be used to measure CD4+ T cell subset infection by clinical isolates, specifically HIV-1 subtype C strains." (PMID 24517971, 2014).